RN7SL335P (RNA, 7SL, cytoplasmic 335, pseudogene)
Gene: Miscellaneous RNA gene on chromosome 4 (122,087,508 to 122,087,811, reverse strand). Ensembl gene ENSG00000241037.
Homologues: Orthologues: chimpanzee Metazoa_SRP (98% identical), macaque Metazoa_SRP (82% identical). Paralogues in human: RN7SL2 (75% identical), RN7SL1 (75% identical), RN7SL296P (74% identical), RN7SL45P (73% identical), RN7SL3 (73% identical), RN7SL7P (73% identical), RN7SL384P (72% identical), RN7SL792P (72% identical), RN7SL145P (72% identical), RN7SL398P (72% identical), RN7SL444P (72% identical), RN7SL648P (72% identical), and 699 more.